CT47A7 (cancer/testis antigen family 47 member A7)
Synonyms: CT47.7
Gene: Protein-coding gene on chromosome X (120,953,282 to 120,956,600, reverse strand). Ensembl gene ENSG00000228517.
Subcellular location (Human Protein Atlas): Nucleoli
Homologues: Orthologues: macaque CT47B1 (77% identical). Paralogues in human: CT47A1 (100% identical), CT47A10 (100% identical), CT47A11 (100% identical), CT47A12 (100% identical), CT47A2 (100% identical), CT47A3 (100% identical), CT47A4 (100% identical), CT47A5 (100% identical), CT47A6 (100% identical), CT47A8 (100% identical), CT47A9 (100% identical), CT47B1 (86% identical), and 1 more.